ATP13A5 (ATPase 13A5)
Synonyms: FLJ16025
Tractability: Antibody: its Gene Ontology location is reachable by antibodies, with high confidence; UniProt predicts a signal peptide or a membrane-spanning region; the Human Protein Atlas places it where antibodies can reach. PROTAC: ubiquitination databases record sites on it.
Gene: Protein-coding gene on chromosome 3 (193,274,789 to 193,378,820, reverse strand). Ensembl gene ENSG00000187527.
Subcellular location: Membrane
Subcellular location (Human Protein Atlas): Plasma membrane; Nucleoplasm
Pathways (Reactome):
Transport of small molecules: Ion transport by P-type ATPases
Gene Ontology:
Molecular function: ATPase-coupled monoatomic cation transmembrane transporter activity; polyamine transmembrane transporter activity; ATP binding; ATP hydrolysis activity; nucleotide binding; P-type ion transporter activity; P-type transmembrane transporter activity
Biological process: intracellular calcium ion homeostasis; monoatomic ion transmembrane transport; polyamine transmembrane transport; monoatomic cation transmembrane transport
Cellular component: late endosome membrane; plasma membrane; membrane
Genetic constraint (gnomAD): Loss-of-function variants: 125 observed, 135.27 expected, observed/expected ratio (o/e) 0.92, 90% interval 0.8 to 1.07. The upper end of that interval is the gene's LOEUF score, 1.07, which puts it in group 4 of 6, group 1 being the genes least tolerant of losing a copy. Missense variants: 1,281 observed, 1,409.8 expected, observed/expected ratio (o/e) 0.91, 90% interval 0.87 to 0.95. Synonymous variants: 465 observed, 513.16 expected, observed/expected ratio (o/e) 0.91, 90% interval 0.84 to 0.98.
Homologues: Orthologues: chimpanzee ATP13A5 (99% identical), macaque ATP13A5 (95% identical), pig ATP13A5 (86% identical), dog ATP13A5 (86% identical), rat Atp13a5 (83% identical), guinea pig ATP13A5 (83% identical), mouse Atp13a5 (83% identical), Drosophila melanogaster anne (37% identical), Caenorhabditis elegans catp-6 (34% identical), zebrafish atp2b2 (16% identical), zebrafish si:dkey-28b4.8 (16% identical), zebrafish atp1a3a (15% identical), and 8 more. Paralogues in human: ATP13A4 (58% identical), ATP13A3 (41% identical), ATP13A2 (37% identical), ATP13A1 (24% identical), ATP2B3 (17% identical), ATP2B1 (17% identical), ATP2B4 (17% identical), ATP2B2 (16% identical), ATP2A3 (16% identical), ATP1A2 (15% identical), ATP2A2 (15% identical), ATP1A1 (15% identical), and 9 more.
Diseases named in the same sentence as ATP13A5 in open-access papers:
ATP13A5 is named in the same sentence as 6 diseases in open-access papers, as found by Europe PMC text mining. Sharing a sentence is not in itself a finding about the gene and the disease. The quoted sentences say what the papers report.
neuroblastoma (1 paper, 2025). Neuroblastoma (NB) is the most common solid, extracranial childhood tumor. "SLC3A2, ATP13A2, ATP13A3 are abundantly expressed in neuroblastoma tumors, while ATP13A4 and ATP13A5 expression is low." (PMID 39981745, 2025).
brain disorder (1 paper, 2024). A disease affecting the brain or part of the brain. "Therefore, the identification of Atp13a5 as a specific BBB pericyte marker will advance our studies in vascular contributions to various brain disorders across the lifespan." (PMID 39261008, 2024).
myopathy (1 paper, 2020). A disease of the muscle in which the muscle fibers do not function properly. "Given that ATP13A5 and statins both act in the same biochemical pathway, we assessed whether salivary creatinine is also associated with statin usage, and could therefore be used as a biomarker for statin-induced myopathy." (PMID 31960908, 2020).
ATP13A5 also shares sentences with these, for which no sentence is quoted: amyotrophic lateral sclerosis (1 paper); neurodegenerative disease (1); Parkinson disease (1).